CSNK1A1L (casein kinase 1 alpha 1 like)
Description:
Casein kinases are operationally defined by their preferential utilization of acidic proteins such as caseins as substrates. It can phosphorylate a large number of proteins. Participates in Wnt signaling (By similarity).
Synonyms: MGC33182; CK1
Tractability: Small molecule: a high-quality ligand is known; it belongs to a druggable protein family. PROTAC: ubiquitination databases record sites on it; a small molecule that binds it is known.
Target class: CK1 protein kinase CK1 family; CK1 protein kinase CK1-a; CK1 protein kinase group; Kinase; Enzyme; Protein Kinase
Gene: Protein-coding gene on chromosome 13 (37,103,259 to 37,105,664, reverse strand). Ensembl gene ENSG00000180138.
Subcellular location: Cytoplasm
Subcellular location (Human Protein Atlas): Cytosol
Gene Ontology:
Molecular function: ATP binding; protein kinase activity; protein serine kinase activity; protein serine/threonine kinase activity
Biological process: negative regulation of canonical Wnt signaling pathway
Cellular component: cytoplasm
Genetic constraint (gnomAD): Loss-of-function variants: 20 observed, 26.01 expected, observed/expected ratio (o/e) 0.77, 90% interval 0.54 to 1.12. The upper end of that interval is the gene's LOEUF score, 1.12, which puts it in group 4 of 6, group 1 being the genes least tolerant of losing a copy. Missense variants: 414 observed, 443.39 expected, observed/expected ratio (o/e) 0.93, 90% interval 0.86 to 1.01. Synonymous variants: 152 observed, 161.17 expected, observed/expected ratio (o/e) 0.94, 90% interval 0.83 to 1.08.
Homologues: Orthologues: chimpanzee CSNK1A1L (99% identical), macaque CSNK1A1L (98% identical), Drosophila melanogaster CG9962 (44% identical), zebrafish ttbk1b (34% identical), zebrafish ttbk1a (33% identical), zebrafish ttbk2a (32% identical), zebrafish ttbk2b (31% identical), Caenorhabditis elegans ttbk-7 (28% identical), Caenorhabditis elegans T05A7.6 (27% identical), Caenorhabditis elegans F59A6.4 (26% identical), Caenorhabditis elegans K11C4.1 (26% identical), Caenorhabditis elegans C08F8.6 (25% identical), and 59 more. Paralogues in human: CSNK1A1 (91% identical), CSNK1D (66% identical), CSNK1E (64% identical), CSNK1G3 (49% identical), CSNK1G2 (49% identical), CSNK1G1 (48% identical), TTBK1 (33% identical), TTBK2 (33% identical), VRK1 (28% identical), VRK2 (28% identical), CDC7 (24% identical), VRK3 (20% identical).
Diseases named in the same sentence as CSNK1A1L in open-access papers:
CSNK1A1L is named in the same sentence as 6 diseases in open-access papers, as found by Europe PMC text mining. Sharing a sentence is not in itself a finding about the gene and the disease. The quoted sentences say what the papers report.
colorectal cancer (2 papers, 2019 to 2024). A primary or metastatic malignant neoplasm that affects the colon or rectum. "Furthermore, somatic mutations in the CSNK1A1L gene have been identified in colorectal cancer." (PMID 38796065, 2024). "In addition, NRG1 is involved in constitutive signalling by aberrant PI3K in cancer, CSNK1A1L in signalling by WNT in cancer, and MUCL1 in defective GALNT12 causes colorectal cancer." (PMID 31797963, 2019).
breast carcinoma (1 paper, 2020). "In breast cancer (BRCA), overexpression of six dark kinases is associated with decreased overall survival (ALPK3, CSNK1A1L, CSNK2A3, NRK, POMK, and PSKH1)." (PMID 33205077, 2020).
melanoma (1 paper, 2017). A malignant, usually aggressive tumor composed of atypical, neoplastic melanocytes. "Some genes seem to show a more specific profile depending on the tumor type, such as C17ORF104, only highly-abundant in the melanoma samples, FUT5 in colon, PAGE1 in ovarian tumor and CSNK1A1L in prostate." (PMID 29190970, 2017).
cancer (3 papers, 2016 to 2019). A tumor composed of atypical neoplastic, often pleomorphic cells that invade other tissues. "With 10 DEG each, 2 biological processes were modulated, cellular responses to external stimuli with genes coding for prostaglandin protein, histone cluster, and heat shock protein and disease with NAG20, NRG1, SLA2, CSNK1A1L (signalling by WNT in cancer)." (PMID 31797963, 2019). "The average for CSNK1A1L was up-regulated for both categories, but more than the double for the diploid cancer cells." (PMID 27465361, 2016). "Given its association with cancer and the indication that there is a gap between available data and curated knowledge, further curation of EPHB1 and CSNK1A1L may be especially valuable." (PMID 29695735, 2018).
Tumor (3 papers, 2016 to 2019). "The casein kinases CSNK1A1L and CSNK1E were down-regulated in neighbouring mucosa and up-regulated in tumour tissue, while CSNK1A1 was down-regulated in both tissue types." (PMID 27465361, 2016).
CSNK1A1L also shares sentences with these, for which no sentence is quoted: ovarian tumor (1 paper).